ADIPOQ (adiponectin, C1Q and collagen domain containing)
Diseases named in the same sentence as ADIPOQ in open-access papers (continued):
Sharing a sentence is not in itself a finding about the gene and the disease.
coronary artery disease (18 papers, 2009 to 2023). "The exact pathways by which genetic variants in the ADIPOQ gene produce coronary heart disease is not well known." (PMID 34073587, 2021). "The adiponectin-encoding gene, ADIPOQ, is located on chromosome 3q27 within a region linked to type 2 diabetes mellitus, metabolic syndrome and coronary artery disease." (PMID 27684940, 2016). "ADIPOQ rs7649121 was linked with reduced risk of coronary heart disease in Chinese." (PMID 29559003, 2018). "Whether adiponectin (ADIPOQ) polymorphisms are associated with coronary artery disease (CAD) remain controversial." (PMID 30885128, 2019). "It has been demonstrated that ADIPOQ worked as a novel modulator for endothelial adhesion molecules, and plasma ADIPOQ concentrations were significantly lower in patients with coronary artery disease early in 1999." (PMID 29156813, 2017). "We aimed to investigate the genetic association between the risk of Coronary Heart Disease (CHD) and the rs3774261, rs1063537 and rs2082940 SNPs of AdipoQ gene; and whether there is an interaction between any existing association and environmental factors, in Northeast Han Chinese populations." (PMID 26754433, 2016).
Hypertension (18 papers, 2011 to 2025). The presence of chronic increased pressure in the systemic arterial system. "Low serum adiponectin level can predict hypertension development, and adiponectin gene (ADIPOQ) polymorphisms have been reported to be linked with hypertension risk." (PMID 36094942, 2022). "In this case-control study, we explored the association among ADIPOQ polymorphisms, serum lipid levels, and hypertension risk in coal miners." (PMID 36094942, 2022). "Our results show that the rs2241766 polymorphism in the ADIPOQ gene is significantly associated with hypertension." (PMID 28181566, 2017). "In the Caucasian subgroup, the rs1501299 polymorphism in the ADIPOQ gene was significantly associated with hypertension." (PMID 28181566, 2017). "A previous study in a Hong Kong Chinese population also suggested that genetic variants in the promoter region of ADIPOQ are associated with increased risk of hypertension." (PMID 24414038, 2014). "Recently, our group has also confirmed that ADIPOQ gene variants are associated with hypertension and adiponectin levels in a Chinese sample." (PMID 23936408, 2013). "Whether the polymorphisms of the ADIPOQ gene are associated with hypertension have attracted growing increased attention." (PMID 28181566, 2017). "Therefore, we performed this meta-analysis to investigate the associations between ADIPOQ rs2241766, rs1501299 and rs266729 polymorphisms and hypertension." (PMID 28181566, 2017). "The ADIPOQ gene has also been implicated in the etiology of hypertension." (PMID 24414038, 2014). "Interestingly, REN and ADIPOQ also present polymorphisms, which seem linked to therapeutic response to hypertension." (PMID 23282288, 2012). "All these findings imply that ADIPOQ might be linked to the presence of hypertension." (PMID 36094942, 2022). "Our results are consistent with those of a previous study that reported reduced expression of ADIPOQ and its receptors (AdipoR1 and AdipoR2) within the perivascular adipocytes of mice with angiotensin II-induced hypertension." (PMID 36157437, 2022). "Future studies seeking to illustrate the biological or clinical potentials of ADIPOQ genetic defects in the pathogenesis of hypertension are very much needed." (PMID 28099908, 2017). "The purpose of the present study was to evaluate the association between four insulin resistance genes (ADIPOQ, LEPR, RETN, and TRIB3) and both T2DM and hypertension." (PMID 24414038, 2014). "In summary, the present findings suggest that variants in ADIPOQ and LEPR are significant risk factors for T2DM and hypertension." (PMID 24414038, 2014). "Recently, two meta-analyses explored the relationship between SNPs rs2241766 and rs1501299 in the ADIPOQ gene and blood pressure and essential hypertension in Chinese populations." (PMID 23593121, 2013). "From these publications, we believe that MDM2 and IGN1 should be part of the apoptosis list, as well as REN and ADIPOQ should be part of the hypertension list." (PMID 23282288, 2012). "Further unearthing of the genetic structure of ADIPOQ might enhance our understanding on the genetic basis of hypertension." (PMID 28099908, 2017). "We found several SNPs in LEPR and ADIPOQ to be significantly associated with T2DM and hypertension." (PMID 24414038, 2014). "Fifth, only three common SNPs were evaluated in our study and other relevant SNPs in ADIPOQ which are unknown or understudied or not studies at all may also have potential associations with hypertension." (PMID 28181566, 2017). "The simultaneous decrease of ADIPOQ expression in the EAT and PVAT may also have an unfavorable affect as this adipokine attenuates vascular damage in hypertension." (PMID 36157437, 2022). "This intersection analysis showed that the final list of shared genes among hypertension, NAFLD, fibrosis and inflammation contained only four genes, including LEP, ADIPOQ, AHR and TGFB1, which could be regarded as important genes related to hypertension and NAFLD." (PMID 34096467, 2021).
gestational diabetes (15 papers, 2015 to 2025). Carbohydrate intolerance first diagnosed during pregnancy. "The genes in the first cluster, with the exception of ADIPOQ, show a strong association with lipid metabolism, while genes in the second and third clusters are associated with type two and gestational diabetes." (PMID 36982283, 2023). "The authors also found that in parallel to reduced mRNA expression, small yet significant alterations in locus-specific DNA methylation of the ADIPOQ gene both in maternal fat and blood cells were associated with gestational diabetes and neonatal outcome as well." (PMID 36527105, 2022). "In Japanese populations, the gestational-diabetes-related loci include adiponectin (ADIPOQ), CDKN2A/2B, signal sequence receptor subunit 1-Ras-responsive element binding protein 1 (SSR1-RREB1), and MyoD family inhibitor domain-containing 2 (MDFIC2)." (PMID 40650275, 2025). "Here we aim to identify individual’s susceptibility to gestational diabetes mellitus (GDM) in the presence of T45G and G276T single nucleotide polymorphisms (SNPs) within the ADIPOQ gene among Filipino pregnant women." (PMID 37953238, 2023). "We studied adipokine plasma levels, SAT gene expression, and DNA methylation of LEP, ADIPOQ, and RETN in adult offspring of women with gestational diabetes (O-GDM, N = 82) or type 1 diabetes (O-T1DM, N = 67) in pregnancy, compared to offspring of women from the background population (O-BP, N = 57)." (PMID 28413567, 2017).
atherosclerosis (12 papers, 2011 to 2023). A disease characterized by the build-up of fatty material and calcium deposition in the arterial wall resulting in partial or complete occlusion of the arterial lumen. "In summary, the current study investigated the association between genetic variants of ADIPOQ gene and risk of atherosclerosis in a Chinese population." (PMID 29156813, 2017). "To find the potential population stratification, we analyzed the associations between ADIPOQ rs74577862 with risk of atherosclerosis stratified by atherosclerosis site." (PMID 29156813, 2017). "Here, we aim to evaluate the association of the genetic variants of ADIPOQ gene with risk of atherosclerosis among a large Chinese population with a case-control study design." (PMID 29156813, 2017). "The current study explored association between genetic variants of ADIPOQ gene (rs74577862 and rs62292784) with risk of atherosclerosis among a large Chinese population." (PMID 29156813, 2017). "The atherosclerosis risk allele of rs74577862 correlated with decreased expression level of ADIPOQ gene (P<0.001)." (PMID 29156813, 2017). "This led to the notion of interactions involving some of the metabolic risk traits and the ADIPOQ gene as a triggering factor for both early and late onset of atherosclerosis." (PMID 24330659, 2013). "Future studies should address the mechanisms of ADIPOQ with regard to the risk of atherosclerosis." (PMID 29156813, 2017). "However, whether ADIPOQ variants were associated with risk of atherosclerosis, especially in a non- European population, is still unknown." (PMID 29156813, 2017). "Another key adipokine, adiponectin (ADIPOQ), is expressed exclusively by mature adipocytes, supports insulin sensitivity, and has a protective effect against cardiac hypertrophy and atherosclerosis." (PMID 32133436, 2019). "Hence, we are of the opinion that one explanation for our finding that SNP rs3774261G is associated with the risk of CHD could be that this AdipoQ polymorphism can cause variations in serum triglycerides leading to atherosclerosis and subsequently to the development of CHD." (PMID 26754433, 2016). "On the other hand, available literature on the role of the adiponectin gene (ADIPOQ) in atherosclerosis remains inconsistent." (PMID 24330659, 2013). "Most important, the results also point to the harbouring by the ADIPOQ 3′UTR of important elements regulating common atherosclerosis disease pathways." (PMID 24330659, 2013). "Our study described the sharing of several ADIPOQ variants by metabolic risk traits among themselves as well as CAD/MI, in support of an important role for this gene in atherosclerosis disease pathways." (PMID 24330659, 2013). "This is because ADIPOQ may protected the aorta from atherosclerosis injury by reducing the oxidative stress, as well as reducing the lesion formation size in the aortic root and reducing TC, TG, and LDL-C in serum." (PMID 29156813, 2017). "Furthermore, we also conducted functional study of ADIPOQ rs74577862 for its role in the development of atherosclerosis." (PMID 29156813, 2017). "Hence, polymorphic changes in the adiponectin Q (ADIPOQ) gene are likely to contribute to metabolic disorders, and consequently lead to atherosclerosis." (PMID 24330659, 2013). "ADIPOQ, which accumulated in the injured artery from the plasma and suppressed endothelial inflammatory response and vascular smooth muscle cell proliferation, could also suppress the development of atherosclerosis in vivo." (PMID 29156813, 2017). "Hence, alterations in circulating adiponectin levels, largely thought to be a consequence of changes in the ADIPOQ gene sequence, constitute potential risk for disorders such as obesity, insulin resistance, T2DM, MS, and consequently susceptibility to acquiring atherosclerosis." (PMID 24330659, 2013).
atherosclerosis (continued). "Some of the RORα-modulated genes are involved in physiological functions such as lipid metabolism (LPA, NR1D2, ADIPOQ also known as adiponectin) and inflammation (ADIPOQ, PLG), but also in related cardiovascular diseases such as atherosclerosis." (PMID 21818335, 2011). "Hence, our present observations raise the all-important question as to whether or not there exists some form of ADIPOQ gene-disease trait interactions paving the pathway(s) to atherosclerosis that are related to these manifestations." (PMID 24330659, 2013).
polycystic ovary syndrome (11 papers, 2018 to 2025). A disorder that manifests as multiple cysts on the ovaries. "Prior to this, ADIPOQ and its receptor had been detected in human ovaries, and ADIPOQ SNPs were associated with polycystic ovaries syndrome." (PMID 39199896, 2024). "Furthermore, research has demonstrated a substantial correlation between ADIPOQ polymorphisms and the risk of developing polycystic ovarian syndrome in people." (PMID 39199896, 2024). "In the present study the ADIPOQ gene was underexpressed, another author observed that the non-presence could be one of the main causes of infertility and associated with pregnancy-related disorders, including polycystic ovarian syndrome." (PMID 33092110, 2020). "ITGAV and ABCA5 have been reported to be associated with ovarian cancer and ADIPOQ and PPARG are associated with polycystic ovary syndrome." (PMID 35052428, 2021).
colorectal cancer (9 papers, 2011 to 2021). A primary or metastatic malignant neoplasm that affects the colon or rectum. "Decreased expression of adiponectin (ADIPOQ) is associated with an increased risk for developing colorectal cancer (CRC) in humans." (PMID 21749709, 2011). "This study systematically evaluated the association between a set of polymorphisms in the ADIPOQ and its receptor genes and colorectal cancer." (PMID 22087284, 2011). "Recently, several lines of evidence have demonstrated the inverse association between serum ADIPOQ and colorectal cancer risk." (PMID 22087284, 2011). "In summary, this is the first study to systematically assess the impact of germ line genetic variants in ADIPOQ and its receptor genes and gene-environment interactions on colorectal cancer risk in Chinese." (PMID 22087284, 2011). "Our GWAS study did not identify a significant association between any of the genotyped SNPs in the ADIPOQ gene and risk of colorectal cancer." (PMID 21829206, 2011). "However, variants of the adiponectin gene (ADIPOQ) have been demonstrated to be inconsistently associated with risk of colorectal cancer." (PMID 21829206, 2011). "Therefore, we performed a two-stage case-control study to systemically evaluate single nucleotide polymorphisms (SNPs) of ADIPOQ and its receptor genes as a predictor of colorectal cancer risk in Chinese population." (PMID 22087284, 2011). "In addition to the interactions inside ADIPOQ signal pathway, the function of ADIPOQ and its receptor genes was also modified by some colorectal cancer risk associated environmental factors, such as smoking status and BMI." (PMID 22087284, 2011). "Our results suggest that variants in ADIPOQ may contribute to increased colorectal cancer risk in Chinese and this contribution may be modified by environmental factors, such as smoking status, family history of cancer and BMI." (PMID 22087284, 2011). "Subsequently, we may infer that rs1063538 could influence colorectal cancer risk by its linkage disequilibrium with other SNPs in the 3'UTR to regulate the expression of ADIPOQ, however, it remained to be confirmed." (PMID 22087284, 2011). "Similar results were obtained when a cis‐acting variant was used as the genetic instrument (ie, rs17366568 in ADIPOQ gene) (overall colorectal cancer; OR = 0.92 [95% CI = 0.82‐1.03]; P = .16)." (PMID 33038280, 2021). "ADIPOQ, ALOX5, and ALOX15 are reportedly associated with lung cancer, colorectal cancer, and colon cancer." (PMID 30071629, 2018). "In the current study, we further evaluated the associations between the variants of ADIPOQ and ADIPOR1 and the colorectal cancer in a southeast Chinese population." (PMID 25516230, 2014). "High level ADIPOQ exposure has been proven to inhibit the proliferation of colorectal cancer cell lines, whereas, knockout of ADIPOQ could promote tumor growth in mice by reducing macrophage infiltration." (PMID 22087284, 2011).
endometrial cancer (8 papers, 2011 to 2025). Primary or metastatic malignant neoplasm involving the endometrium (mucous membrane that lines the endometrial cavity). "In our earlier study in which we analyzed the role of ADIPOQ (NM_004797.4):c.214+62G>T (rs1501299) in Endometrial Cancer, patients treated for uterine leiomyomas were used as Controls." (PMID 35250389, 2021). "The increased mRNA expression of adiponectin (ADIPOQ), leptin, IL6, and TNFα in endometrial cancer tissue highlights an enhanced inflammatory and metabolic state within the tumor microenvironment, which may drive cancer progression." (PMID 40642843, 2025).
myocardial infarction (7 papers, 2011 to 2025). Gross necrosis of the myocardium, as a result of interruption of the blood supply to the area, as in coronary thrombosis. "Observationally, increased plasma levels are associated with a heightened risk of heart failure, AFib, aortic valve stenosis, and myocardial infarction (MI), while another study found that reduced AdipoQ levels were associated with AFib." (PMID 38999835, 2024).
Abdominal obesity (6 papers, 2011 to 2023). Excessive fat around the stomach and abdomen. "Our findings indicate that there is an interaction between the ADIPOQ gene and central obesity, which provides new insights into the prevention and treatment of T2DM." (PMID 32685510, 2020). "GMDR analysis revealed that the ADIPOQ SNPs had interactions with central obesity." (PMID 32685510, 2020).
Hyperglycemia (6 papers, 2015 to 2023). An increased concentration of glucose in the blood. "ADIPOQ and IGFBP2 were associated with the four incident components with significant results namely increased waist circumference, hypertriglyceridemia, hyperglycemia and increased blood pressure." (PMID 34016094, 2021). "The mRNA levels of RUNX2, PPARγ and AdipoQ were also correlated with adipogenesis, which shows chronic hyperglycemia favoring adipogenesis." (PMID 29988028, 2018). "In addition, a significant difference was found in the gene variants associated with the risk of DM2 in the Crimean population, which helped to establish the relationship between carrying the ADIPOQ gene’s GG (rs1501299) genotype and hyperglycemia." (PMID 35366291, 2022). "The decreased ADIPOQ expression and increased average ADIPOQ methylation in O-GDM remained significant after adjustment for potential confounders and mediators, implying a role for hyperglycemia in pregnancy in causing these changes." (PMID 28413567, 2017).
prostate carcinoma (6 papers, 2011 to 2024). A carcinoma that arises from epithelial cells of the prostate gland. "Other alterations with a tumor-inhibitory impact would be inhibition of ADIPOQ, associated with prostate cancer progression risk, and HNF1A/4A, recently proposed as oncogenic in pancreatic cancer." (PMID 34209203, 2021).
Alzheimer disease (5 papers, 2019 to 2024). A progressive, neurodegenerative disease characterized by loss of function and death of nerve cells in several areas of the brain leading to loss of cognitive function such as memory and language. "Several promising studies of the role of AdipoQ signaling in physiopathological processes associated with Alzheimer’s disease." (PMID 33584324, 2020). "Several studies found that patients with moderate cognitive impairment (MCI) and Alzheimer's disease (AD) have higher levels of ADIPOQ in their plasma than healthy people." (PMID 36527105, 2022).
asthma (5 papers, 2011 to 2023). "Numerous genetic variations linked to obesity-related asthma have been pinpointed in research studies, encompassing ADIPOQ, retinoid-related orphan receptor C (RORC), IL17A, TNF-α, beta-2 adrenergic receptor (ADRB2), and IL-6." (PMID 37834850, 2023). "Polymorphisms of the ADIPOQ gene, in particular the G allele of rs822396 and T allele of rs1063537, were associated with an increased risk for asthma, while variants rs11760956, rs11763517 and rs2167270 were protective." (PMID 34445677, 2021). "In Brazil, protection against asthma and atopy attributed to variants on the genes for leptin (LEP) and adiponectin (ADIPOQ) were lost in overweight individuals." (PMID 36973960, 2023).